VCP (valosin containing protein)
Diseases named in the same sentence as VCP in open-access papers (continued):
Sharing a sentence is not in itself a finding about the gene and the disease.
A further 68 diseases each share a sentence with VCP in 1 paper.